BDNF (brain derived neurotrophic factor)
Diseases named in the same sentence as BDNF in open-access papers (continued):
Sharing a sentence is not in itself a finding about the gene and the disease.
breast cancer (continued). "However, our in vitro and ex vivo data are in concordance with the BDNF expression found in public data sets underscoring a putative suppressive function of BDNF in human breast cancer and a potential association to the Wnt pathways." (PMID 25036590, 2014). "BDNF has also been implicated in several human malignancies, including breast cancer (BC)." (PMID 21767406, 2011). "The converse functional data might be caused by the fact that BDNF expression is down-regulated in luminal as well as basal A breast cancer cells while mesenchymal basal B breast cancer cells such as MDA-MB231 showed increased expression levels (GOBO data set analysis, data not shown)." (PMID 25036590, 2014). "Previous studies linking plasma cytokine and/or BDNF levels to CRCI have focused mainly on breast cancer patients and lack a relevant comparison group." (PMID 40597835, 2025). "This interpretation is plausible, as an increase in microglia-derived BDNF has also been described in different pathological contexts, including breast cancer." (PMID 41155372, 2025). "Studies have demonstrated that an elevated NAS/melatonin ratio promotes breast cancer cell survival and metastasis by mimicking brain-derived neurotrophic factor (BDNF) through TrkB receptor activation." (PMID 40654575, 2025). "mmu-miR-191 was found to be upregulated in eEVs by 2.5-fold compared with sEVs, and increased expression has been shown to increase levels of brain-derived neurotrophic factor (BDNF) in a human breast cancer cell line." (PMID 39898049, 2025). "For example, BDNF showed a strong negative correlation with multiple proinflammatory markers including IFN‐γ, IL‐1β, IL‐4, IL‐8 in people with early‐stage breast cancer, and BDNF has been shown to have direct anti‐inflammatory effects." (PMID 40317574, 2025). "This highlights the importance of further investigating the role of BDNF in breast cancer, as previous studies have shown that the expression of its receptor TrkB, particularly the TrkB.T1 isoform, increases tumor resistance to apoptosis." (PMID 41155372, 2025). "Multiple randomized controlled trials (RCTs) have demonstrated that acupuncture therapy enhances the management of CRCI in breast cancer patients, potentially attributed to an increase in brain-derived neurotrophic factor (BDNF)." (PMID 39913618, 2025). "For example, miR-191-5p regulates cortical development by targeting brain-derived neurotrophic (factor BDNF), and promotes the proliferation and migration of human breast cancer cells by targeting special AT-rich sequence-binding protein-1 (SATB1)." (PMID 39469460, 2024). "In the current study, we explored the possibility of employing BDNF, NT-3 and galectin-3 as biomarkers to identify lesions of the peripheral nervous system in women following breast cancer treatment." (PMID 37092524, 2023). "In our past clinical studies, we consistently observed a statistically significant decrease in plasma BDNF levels at 6 and 12 weeks after breast cancer patients were treated with ADR and cyclophosphamide (ADR-CYP)." (PMID 36720792, 2023). "In our clinical studies, breast cancer patients treated with doxorubicin (Adriamycin®, ADR) experienced a significant reduction in the blood levels of BDNF that was associated with a higher risk of CRCI." (PMID 36720792, 2023). "SFRP1 interferences with Wnt signaling to block the ligand-receptor interaction or co-regulates with BDNF to have a potential inhibitory effect on breast cancer." (PMID 37963835, 2023). "For instance,high levels of BDNF are significantly correlated with the poor overall survival of breast cancer patients." (PMID 37460933, 2023). "Previously, we have shown that elevated levels of pro-inflammatory cytokines IL-1β and IL-6 corresponded with poorer cognitive response and higher BDNF levels were protective against persistent CRCI in a cohort of early stage breast cancer (ESBC) patients." (PMID 33985854, 2021).
breast cancer (continued). "Interruption of physiological BDNF function was correlated with neurodegeneration, neuropathic pain, psychiatric disorder, breast cancer, ovarian cancer, and gastric cancer." (PMID 33604392, 2021). "Brain-derived neurotrophic factor (BDNF) is a potent neurotrophic factor that has been shown to stimulate breast cancer cell growth and metastasis via tyrosine kinase receptors." (PMID 32190687, 2020). "Our in vitro study showed that short-term hyperoxia exposure of breast cancer cells increases ROS, increased BDNF expression that promotes EMT and angiogenesis." (PMID 32183322, 2020). "We had previously demonstrated that the BDNF Val66Met genetic polymorphism is associated with lower odds of subjective CRCI in the multitasking and verbal ability domains among breast cancer patients receiving chemotherapy." (PMID 30382534, 2019). "Previously, using genomic microarray analysis of paired (non-recurrent and recurrent) resected tumor tissues obtained from breast cancer patients, activation of the BDNF pathway has been found to be crucial to the clinical recurrence of TNBC tumors." (PMID 28604807, 2017). "To our knowledge, we are the first to investigate the role of BDNF in cancer cell-endothelial cell interactionsusing breast cancer cells." (PMID 28604807, 2017). "It was further reported that the mammary cancer specimens have a high level of BDNF as compared to normal tissue of human subjects." (PMID 28420987, 2017). "The level of BDNF in mammary tumors was measured on the 5th day after the administration of CUR, CIS, and combination of CUR with CIS." (PMID 28420987, 2017). "Because the brain microenvironment contains high concentrations of BDNF, we proposed that paracrine signaling between astrocyte-derived BDNF and TrkB on breast cancer cells supports successful initial brain colonization." (PMID 28446206, 2017). "The observation of the present study is that activation of PPAR-γ and inactivation of BDNF in mammary tissue inhibited the growth of breast cancer in rats." (PMID 28420987, 2017). "We measured the BDNF level in the cultured media of various different breast cancer cell lines and the results showed that the MDA-MB-231 cells, but not the various other cell types, secrete BDNF into the culture media in a time-dependent manner." (PMID 28800782, 2017). "Anticancer activity was assessed by measurement of tumor weight, tumor volume, % tumor inhibition, levels of PPAR-γ, and BDNF in mammary tumors and histopathology of mammary tumors." (PMID 28420987, 2017). "CUR pre-treatment for 5 days followed by single injection of CIS significantly reduced BDNF expression and inhibited progression of mammary cancer." (PMID 28420987, 2017). "BDNF/TrkB signaling plays important roles in tumor metastasis and is recognized as a therapeutic target in treatment of breast cancer." (PMID 28604807, 2017). "In terms of the protein's molecular and clinical roles, BDNF has been reported to be a target marker for predicting clinical outcomes in breast cancers." (PMID 28604807, 2017). "A previous study claimed that higher level of BDNF is significantly related to breast cancer development and its prohibition leads to reduced tumor cell survival." (PMID 28420987, 2017). "Previous research suggests that autocrine signaling in breast cancer cells is responsible for BDNF-TrkB-induced metastasis." (PMID 28446206, 2017). "We found that Her2+ breast cancer cells have increased TrkB protein levels in response to astrocyte-derived BDNF stimulation, resulting in the formation of TrkB and Her2 heterodimers and brain metastases." (PMID 28446206, 2017). "The cumulative treatment of CUR plus CIS augmented the expression of PPAR-γ while lessening the expression of BDNF in mammary tumors." (PMID 28420987, 2017).
breast cancer (continued). "This notion is underscored by the observation of Dooley and colleagues who noted a positive association between C-reactive protein levels and cognitive depressive symptoms among BDNF Met carriers of breast cancer survivors." (PMID 28056856, 2017). "The stimulus of resistance to apoptosis by BDNF suggests their possible value as therapeutic targets in breast cancer, that provide new directions for the invention of innovative strategies based on neurotrophin inhibition." (PMID 28420987, 2017). "Although the role of BDNF in breast cancer remains controversial, it has become important to elucidate the effects of Chinese herbal medicines on BDNF production by cancer cells." (PMID 28800782, 2017). "The up-regulation of BDNF was found in a variety of primary human tumors, including breast cancer, hepatocellular carcinoma, and bladder cancer, suggesting a significant role of BDNF in the development and progression of cancer." (PMID 26926340, 2016). "BDNF expression has been shown to significantly impact breast cancer cell survival, to be a pro-oncogenic target of microRNAs in breast cancer, and to be associated with decreased patient survival in breast cancer." (PMID 26087699, 2015). "BDNF has a critical role in tumorigenesis, promoting proliferation, differentiation, angiogenesis and invasiveness in several tumor types, including breast cancer." (PMID 26042423, 2015). "In contrast to recent published studies highlighting BDNF as a putative oncogene, the Kaplan-Meier data of the independent patient data set suggested rather suppressive characteristics of BDNF in breast cancer development." (PMID 25036590, 2014). "The role of BDNF as a prognostic marker in breast cancer has been postulated because increased BDNF expression has been found in breast cancer tissue." (PMID 25309465, 2014). "In summary we assessed that forced SFRP1 expression in BT20 and SKBR3 breast cancer cells leads to an induction of BDNF expression." (PMID 25036590, 2014). "In line, we functionally provide evidence that stable BDNF re-expression in basal-like BT20 breast cancer cells blocks tumor cell proliferation." (PMID 25036590, 2014). "Therewith, we propose at this step a putative suppressive function of BDNF for this clinical important subgroup of basal-like breast cancer." (PMID 25036590, 2014). "They showed that BDNF is expressed and secreted in breast cancer cells and functionally contributes to cancer cell survival." (PMID 25036590, 2014). "In human breast cancer, there was substantially greater BDNF expression within neoplastic cells compared with normal mammary epithelial cells." (PMID 23531103, 2013). "Recent studies have shown that high expression levels of BDNF have a significant relationship with the tumorigenesis, progression, biological behavior, and prognosis of breast cancers." (PMID 23531103, 2013). "To determine if BDNF or NTF3 activate TrkB signaling in a breast cancer model, we stably transfected empty vector (EV) or TrkB into MCF7 and T47D cells." (PMID 23185507, 2012). "Offspring of these mice show enhanced development of mammary tumours with increased mRNA and protein expression of BDNF and TrkB." (PMID 21767406, 2011). "Western immunoblot confirmed the increased mRNA expression translated to increased protein expression in mammary tumors with both TrkB and BDNF expression increased in mammary tumors from dieldrin treated mice." (PMID 19173004, 2009). "In this context, cytokines and brain-derived neurotrophic factor (BDNF) could serve as biomarkers to detect CRCI in patients with breast cancer." (PMID 41155372, 2025). "Additionally, researchers discovered a BDNF signaling pathway that inhibits breast cancer by regulating specific kinases and cytokines." (PMID 39648800, 2024).
breast cancer (continued). "LINC00922 is obviously overexpressed in breast cancer tissues and cell lines, and therefore increasing the expression of the miR-424-5p/BDNF axis can reduce the expression of LINC00922 and weaken its effects on promoting the proliferation, apoptosis, migration and invasion of breast cancer cells." (PMID 35409396, 2022). "The methylation of BDNF gene may be a biomarker for suicidal thoughts in patients with breast cancer." (PMID 32190687, 2020). "The upregulation of BDNF can promote breast cancer cell proliferation and invasion." (PMID 33536908, 2020). "BDNF has been understudied in breast cancer survivors; however, a review of randomized controlled trials of physical activity interventions in noncancer populations found improvements in BDNF in 3 out of 5 trials, with 2 of the trials being longer than 6 months." (PMID 31605514, 2019). "In addition, microenvironmental BDNF-mediated activation of TrkB resulted in increased metastatic potential of Her2+ cells and formation of Her2-TrkB heterodimers on breast cancer cells." (PMID 28446206, 2017). "While controversy that BDNF predicts adverse pathological and clinical outcome in breast cancer patients remains, the precise mechanism by which BDNF is involved in cancer cell signaling, and how BDNF affects the microenvironment of breast cancers, is need to be further elucidated." (PMID 28604807, 2017). "Interestingly, CUR plus CIS combination presented maximum fall in BDNF level as compared to CUR or CIS treated breast cancer rats." (PMID 28420987, 2017). "However, the possible paracrine role of TrkB activation by BDNF in the brain microenvironment in metastatic Her2+ breast cancer needs to be further elucidated." (PMID 28446206, 2017). "Nonetheless, the role of brain-derived neurotrophic factor (BDNF) in the interaction between breast cancer cells and endothelial cells interaction remains unknown." (PMID 28604807, 2017). "In addition, we investigated a possible interaction between TrkB and Her2 receptors on brain metastatic breast cancer cells, and found that BDNF phosphorylated both its cognate TrkB receptor and the Her2 receptor in brain metastatic breast cancer cells." (PMID 28446206, 2017). "We hypothesized that neoplastic cells, including metastatic Her2+ breast cancer cells, in the brain microenvironment use BDNF produced and released by surrounding astrocytes." (PMID 28446206, 2017). "In addition, we analyzed the survival outcome of TNBC breast cancer patients according to their expression level of BDNF using clinical samples." (PMID 28604807, 2017). "In addition, overexpressing miR-191 increased the expression of endogenous BDNF in MCF7 cells (a breast cancer cell line), and suppressing endogenous miR-191 expression using a specific antagomiR decreased BDNF levels." (PMID 25601223, 2015). "Furthermore, to our best knowledge the current findings propose for the first time that BDNF is a target gene of SFRP1 with putative suppressive characteristics in breast cancer, thus highlighting its clinical relevance in a completely different and novel way." (PMID 25036590, 2014). "Further analysis of the functional impact of BDNF on basal-like BT20 breast cancer cells supported our hypothesis that BDNF might rather mediate growth inhibiting than promoting properties." (PMID 25036590, 2014). "However, combined analysis of weak BDNF and weak SFRP1 expression predicted also an unfavorable patients' outcome underscoring the significance of the breast cancer model-based SFRP1/BDNF expression axis." (PMID 25036590, 2014). "This positive correlation in vitro may be maintained in vivo due to the tight correlation detected between SFRP1 and BDNF mRNA in human breast cancer samples." (PMID 25036590, 2014). "Therefore, we performed immunohistochemical staining of SFRP1 and BDNF on a breast cancer tissue microarray comprising 144 specimens." (PMID 25036590, 2014).
breast cancer (continued). "However, Yang and co-workers recently demonstrated that a knockdown of BDNF resulted in a reduced cell proliferation in the breast cancer cell line MDA-MB231." (PMID 25036590, 2014). "It was a clear objective to subsequently study whether the correlation between SFRP1 and BDNF expression in primary breast cancer samples is preserved on the protein level as well." (PMID 25036590, 2014). "Moreover, TCGA dataset based analysis clearly underscores that BDNF mRNA is down-regulated in primary breast cancer samples predicting a poor prognosis of these patients." (PMID 25036590, 2014). "Thus, the immunohistochemical analysis of human breast cancer specimens again confirmed that BDNF is a potential “SFRP1 target gene” as originally predicted by our microarray analysis." (PMID 25036590, 2014). "Further studies might be of interest to in depth analyze BDNF function in human breast cancer subtypes helping to explain the striking contradictions." (PMID 25036590, 2014). "Hence, these data generated in our work in comparison with recent publications illustrate a large discrepancy with respect to the function of BDNF in breast cancer." (PMID 25036590, 2014). "To assess the potential relevance of this hypothesis, we analyzed BDNF gene expression and its clinical impact in a large dataset of independent studies, in total representing 3.910 different breast cancer samples." (PMID 25036590, 2014). "Further support for the oncogenic function of BDNF in vivo comes from a transgenic mouse model of spontaneous mammary tumor formation, following exposure to the organochlorine pesticide Dieldrin, which is a persistent environmental toxin thought to increase the risk of BC." (PMID 21767406, 2011). "While the role of TrkB/BDNF signaling in breast cancer is currently unknown, evidence from other malignancies supports a role for this pathway in tumor progression and clinical prognosis and thus merits further exploration." (PMID 19173004, 2009). "Moreover, BDNF is released from breast cancer cells and promotes breast cancer progression." (PMID 37566075, 2023). "Thus, they concluded that a decline in BDNF level might lead to an attenuation of breast cancer cell growth and metastasis." (PMID 34395067, 2021). "BDNF is one of the molecules that are upregulated in response to hyperoxia exposure, as shown in various experimental settings, including the peribronchial smooth muscle of neonatal rats, the Alzheimer mouse model, the breast cancer mouse model and healthy volunteers." (PMID 34572400, 2021). "Likewise, in the present work, we also noted higher levels of BDNF in breast cancer tissue." (PMID 28420987, 2017). "TrkB knockdown in breast cancer cells led to decreased frequency and growth of brain metastasis in animal models, suggesting that circulating breast cancer cells entering the brain may take advantage of paracrine BDNF-TrkB signaling for colonization." (PMID 28446206, 2017). "Indeed, a positive correlation between SFRP1 and BDNF protein expression could be shown (p<0.001) in primary breast cancer samples." (PMID 25036590, 2014). "Hence, our results suggest that BDNF might rather mediate suppressive than promoting function in human breast cancer whose mode of action should be addressed in future studies." (PMID 25036590, 2014). "Studies have further identified BAX as one of the most critical regulatory factors in the BDNF signaling pathway, promoting BAX protein expression and the generation of apoptosis‐related proteins Bax and Bcl‐xL in breast cancer cell lines." (PMID 39648800, 2024). "The PPI results showed that its key targets for breast cancer include PPARG, TLR-4, BDNF, and PPAR-α." (PMID 33536908, 2020). "Further, it reduced mammary cancer via increasing the expression of PPAR-γ (p < 0.001) and decreasing the expression of BDNF (p < 0.001) in mammary tumors." (PMID 28420987, 2017).